MMP7 (matrix metallopeptidase 7)
Diseases named in the same sentence as MMP7 in open-access papers (continued):
Sharing a sentence is not in itself a finding about the gene and the disease.
colorectal cancer (continued). "In addition, we suggest that MMP-7 induces poor prognoses in colorectal cancer by promoting cell viability depending on the cell proliferation." (PMID 26344692, 2015). "Therefore, we revealed for the first time that integrin-α2 increased MMP-7 expression in colorectal cancer." (PMID 26344692, 2015). "Beta-catenin is knowm to regulate the expression of the MMP7 in human colorectal cancer." (PMID 24143235, 2013). "MTG16 is also downregulated in colorectal carcinoma (CRC), where it plays an important role in Kaiso-directed repression of the colon cancer promoting gene MMP-7." (PMID 29358956, 2017). "Moreover, MMP7 is an independent prognosis factor for survival in patients with colorectal cancer." (PMID 19266094, 2009). "In support of this hypothesis, we show that securin, like 12 well-known β-catenin/TCF target genes (e.g. c-myc, c-Met, survivin and MMP7), is significantly overexpressed in colorectal cancer compared to normal mucosa using DNA microarray analysis, real-time PCR and immunohistochemistry." (PMID 16705313, 2006). "In our study, TCGA analysis revealed that genes such as those from the SPRR family, MUC6, KRT family, SLC26A9, MMP7, PRSS56, and SFRP1 were highly expressed in the colorectal cancer group." (PMID 41595533, 2026). "A heatmap of the top 50 differentially expressed genes was generated, highlighting that genes such as SPRR family members, MUC6, KRT family genes, SLC26A9, MMP7, PRSS56, and SFRP1 were highly expressed in the colorectal cancer group." (PMID 41595533, 2026). "In this study, we explored that the relative expression of the Col1a2, ITIH4, MMP7, and MSX2 are increased in the mice who induced colorectal cancer (the COL group) compared with the Normal group." (PMID 38637796, 2024). "The gene profiles (Col1a2, ITIH4, MMP7, and MSX2) were identified as critical markers in colorectal cancer." (PMID 38637796, 2024). "In terms of miR-139-5p role in inflammation, overexpression of miR-139-5p was found to inhibit MMP9, MMP7, cell proliferation, and pro-inflammatory cytokines (IL-1β, IL-6, TNF-α) in colorectal cancer cell lines." (PMID 37474869, 2023). "β-Carotene reduces invasiveness with a decreased expression of MMP-7 and MMP-28 in colorectal carcinoma cells." (PMID 33809289, 2021). "Interestingly, previous investigations have demonstrated that overexpression of MMP7 may contribute to many malignant tumours, including colorectal cancer, pancreatic cancer, lung cancer, and prostate cancer, indicating that MMP7 could be a critical molecular biomarker for oncogenicity." (PMID 31937294, 2020). "We also show that colorectal cancer cells with higher SREBP1 are more invasive, and express higher levels of MMP7, the expression of which is regulated via ROS and the NF-κB pathway." (PMID 31299935, 2019). "Consistently with MMP7 and MMP10 also overexpression of MMP12 in colorectal cancer specimen is reported." (PMID 27431388, 2016). "Together, these results suggested that integrin-β1 and integrin-α2 upregulated MMP-7 expression through YAP, MRLC and EGFR by generating a positive feedback loop on stiffer substrates in colorectal cancer." (PMID 26344692, 2015). "In summary, we demonstrated that stiffer substrates enhanced MMP-7 expression by generating a positive feedback loop involving EGFR, integrin-β1, integrin-α2, MRLC and YAP on stiffer substrates in colorectal cancer." (PMID 26344692, 2015). "We next sought to compare the expression levels of Kaiso, MMP-7 and MTG16 in patients with colorectal cancer compared with normal adjacent colon tissues and adenomas." (PMID 23251453, 2012). "When the data were combined, a combination of MMP-7 and SLC5A8 (and, to a lesser extent, RECK) provided the greatest separation between healthy colon tissue and colorectal cancer (tissue or cell lines)." (PMID 19689820, 2009).
colorectal cancer (continued). "In addition, several Matrix Metalloproteinases (MMPs) such as MMP1 or MMP7, which regulate cancer invasiveness by modulating extracellular matrices degradation are regulated by high levels of ETV1 in prostate and colorectal cancers." (PMID 40275610, 2025). "Growing evidence has indicated that the genes of Col1a2, ITIH4, MMP7, and MSX2 profiles could be critical markers for identifying colorectal cancer." (PMID 38637796, 2024). "Expression of MMP-1 and MMP-7 was elevated in patients with primary colorectal cancer with or without liver metastasis." (PMID 34502094, 2021). "For example, multiplex quantification of ovarian and colorectal cancer biomarkers: matrix metalloproteinases 2 and 7 (MMP-2 and MMP-7, respectively) was performed by an electrode array modified with peptide-specific substrates for MMP-2 and MMP-7." (PMID 32585936, 2020). "In this study, we also showed that in contrast to MMP24, high expression of MMP7, which is another YAP-TEAD target gene, is associated with poor prognosis in lung cancer, pancreatic cancer, and renal cancer but not colorectal cancer." (PMID 32093160, 2020). "In previous studies, we investigated the roles of MMPs including MMP2, MMP7, MMP8, MMP9 and MMP13 in the mice colorectal cancer model tissue, and observed that MMP7, MMP8, MMP9 are more important in colorectal cancer invasion and migration, and that MMP7 is regulated by NF-κB pathway." (PMID 31299935, 2019). "Also, due to the down-regulation of MMP-7 expression by caperatic acid and physodic acid, we hypothesized that these compounds may affect cell invasion as a recent report has shown that the silencing of β-catenin in colorectal cancer cells blocked invasion by reducing MMP-7 and inducing E-cadherin." (PMID 28887754, 2018). "We determined whether the effects of fibulin-5 on lung cancer invasion and MMP-7 expression are mediated by Wnt/β-catenin signaling, which is known to regulate MMP-7 expression in colorectal cancer cells." (PMID 25909283, 2015). "These experimental results indicated that substrate stiffness regulated MMP-7 expression in colorectal cancer and that this regulation was independent of the presence of collagen-I." (PMID 26344692, 2015). "It was observed that a thorough immuno-histochemical analysis of PKP3 and MMP7 levels in a large dataset of colorectal cancer patients has not been performed to determine if any correlation exists between PKP3 and MMP7 levels." (PMID 25875355, 2015). "This is a clear indication that MMP-2 is a key factor in the regulation of cell migration, however it should not be ruled out that other ECM degrading MMPs such as MMP-1, MMP-7, MMP-9 and MMP-13 have been shown be associated with Colorectal cancer progression." (PMID 24130681, 2013). "Different studies showed that some MMP, including MMP2, MMP7 and MMP9 are expressed in colorectal adenomas that are well established premalignant lesions of colorectal cancers, implying their role other than extracellular matrix destruction and metastasis in cancer development and progression." (PMID 17125518, 2006). "In line with our observation, it has been reported that in the absence of distinct TCF7L2 variants the regulation of common TCF/LEF target genes such as cyclin D1, c-myc, MMP7 and c-jun is not detectable in renal cell carcinoma and colorectal cancer cell lines." (PMID 21281469, 2011). "Although the relevant substrates for MMP-7 and MMP-9 in colorectal cancer progression are currently not known, meta-analyses have shown that high expression of either protease strongly predicts poor overall survival." (PMID 29731961, 2018).
gastric cancer (90 papers, 2002 to 2025). A primary or metastatic malignant neoplasm involving the stomach. "A study that evaluated gastric cancer risk with MMP7 SNP in the Eastern Indian population also reported a higher risk associated with the GG genotype." (PMID 38638796, 2024). "To obtain more conclusive results, we recommend determining the association between MMP-7 expression and the survival of gastric cancer patients in future studies." (PMID 35496040, 2022). "Our results showed that high serum CEA levels were associated with high expression of MMP-7 protein in gastric cancer patients." (PMID 35496040, 2022). "We further observed a significant association of the variant genotype; gastric cancer patients carrying GG of MMP-7 rs11568818 had a greater increased risk of MMP-7 expression than those carrying the AA and AG genotypes." (PMID 35496040, 2022). "The association between MMP-7 expression level and clinicopathological characteristics was also evaluated to assess the value of MMP-7 as a possible candidate marker for predicting individuals with higher risk of developing gastric cancer." (PMID 35496040, 2022). "Our results were obtained by analyzing 400 gastric cancer patients treated at three centers in Thailand and showed that elevated expression of MMP-7 is associated with clinicopathological outcomes related to poor prognosis in gastric cancer." (PMID 35496040, 2022). "Several studies have suggested the essential importance of MMP-7 polymorphisms as a risk factor and as a marker of poor prognosis in multiple types of cancer, including gastric cancer." (PMID 35496040, 2022). "To do this, we measured the expression of MMP-7 protein and its polymorphisms (rs11568818) in gastric cancer tissues." (PMID 35496040, 2022). "The results of this study revealed high expression of MMP-7 in gastric cancer and showed a significant association of MMP-7 expression with poor clinicopathological outcome." (PMID 35496040, 2022). "In this study, we aimed to determine the expression of the MMP-7 protein and its polymorphisms in gastric cancer tissues." (PMID 35496040, 2022). "Reports showed that the expression of MMP7 is associated with the poor prognosis of gastric cancer and is involved in the epithelial-mesenchymal transition of the tumor to induce metastasis." (PMID 34157940, 2021). "Pathogenic strains of Helicobacter pylori, which have a greater capacity to cause gastric cancer, induce MMP7 expression in a cag pathogenicity island-dependent manner." (PMID 30696739, 2019). "MMP-7 has been reported to be produced by gastric carcinoma cells and is significantly associated with the aggressive pathological phenotypes of gastric cancer." (PMID 23840737, 2013). "Cag-positive H. pylori significantly upregulate the EMT-associated genes Snail, Slug and vimentin in association with the induction of MMP-7, suggesting a role for these proteins in gastric cancer development." (PMID 22662230, 2012). "Several lines of evidence indicate that the expression of MMP-7 is associated with advanced clinicopathological stages and unfavorable prognosis in gastric cancer." (PMID 20939893, 2010). "The overexpression of MMP-7 was frequently at the invasive front of human gastric cancer and directly associated with prognosis in patients with gastric cancer." (PMID 20939893, 2010). "MMP-7 is also identified as a target of gastrin in hypergastrinemia that is associated with gastric cancer." (PMID 20939893, 2010). "The presence of Hp is associated with the development of gastric cancer and stimulation of MMP-7 production by Hp in human gastric epithelial cells has previously been suggested as a possible mechanism predisposing towards gastric neoplasia." (PMID 16940985, 2006). "This contrasts in part with several other studies reporting not only a clear association between MMP-7 expression and gastric cancer progression but also with survival." (PMID 16538217, 2006).
gastric cancer (continued). "In addition, MMP-7 expression has been shown to be associated with an aggressive malignant phenotype and worse prognosis in patients with gastric cancer." (PMID 35496040, 2022). "Here, we aimed to examine whether the expression of MMP-7 and the presence of this polymorphism can be used to predict the prognosis of gastric cancer." (PMID 35496040, 2022). "The GG genotype of MMP7 A-181G was identified as a risk factor for gastric cancer." (PMID 34485109, 2021). "Chemerin-triggered activation of MMP-7 expression is considered to be an important molecular mechanism underlying the increased invasiveness of gastric cancer cells, as this protease facilitates tumor cell invasion by degradation of extracellular matrix components, E-cadherin and integrins." (PMID 31370263, 2019). "Further studies are needed to assess association of serum MMP7 and the prognosis of gastric cancer." (PMID 25919283, 2014). "Recent studies showed that MMP-7 expression was selectively up-regulated by pathogenic strains of Helicobacter pylori in Helicobacter pylori gastritis, which is considered as the initial stage in the progression to gastric carcinoma." (PMID 20939893, 2010). "In cultured human gastric cancer cells, EA treatment hindered the acidic microenvironment-induced upregulation of MMP7 and MMP9 mRNAs as well as tumor migration and invasion." (PMID 40386045, 2025). "Helicobacter pylori infection is a unique risk factor for gastric cancer, and some studies found that Helicobacter pylori increased EMT in gastric cancer through its cooperative network involving MMP-7, VEGF, and gastrin." (PMID 38737444, 2024). "CXCL1 and MMP7 showed the most significant and highest differential upregulation in gastric cancer samples compared to the healthy stomach." (PMID 36614235, 2023). "Under acidic conditions, gastric cancer cells become more invasive, with elevated expression of MMP-7 and MMP-9." (PMID 38002335, 2023). "In this study, high expression of MMP-7 occurred more often in undifferentiated-type gastric cancer than in differentiated gastric cancer and showed an association with depth of invasion by the tumor and with lymph node metastasis." (PMID 35496040, 2022). "MMP-7 expression also showed a statistically significant association with higher TNM staging and undifferentiated-type gastric cancer." (PMID 35496040, 2022). "Very early studies demonstrated an enhanced expression of MMP-7 in premalignant gastric lesions and gastric cancer." (PMID 35163805, 2022). "Then, a novel TGF-β-associated prognostic model, including SRPX2, SGCE, DES, MMP7, and KRT17, was constructed, and the risk score was demonstrated as an independent prognostic factor for gastric cancer patients." (PMID 36467074, 2022). "The results of our study are consistent with previous reports demonstrating higher MMP-7 expression (70.75%) in gastric cancer patients." (PMID 35496040, 2022). "The MMP-7 wild-type genotype (AA) was observed in 69% of the 400 gastric cancer patients in our study, whereas 17% were heterozygous (AG) and 14% were homozygous (GG) for the mutation." (PMID 35496040, 2022). "Our results show that gastric cancer patients who carry the GG genotype of MMP-7 rs11568818 were more likely to exhibit high MMP-7 expression, resulting in enhanced tumor progression and poor prognosis of these patients." (PMID 35496040, 2022). "Overexpression of MMP-7 has been found in several human cancers, including breast, colon, esophageal, and gastric cancer." (PMID 35496040, 2022). "We found that MMP-7 expression was associated with lymphatic and vascular invasion, suggesting a role for MMP-7 in invasion and metastasis in gastric cancer." (PMID 35496040, 2022). "Among them, HEYL, MMP7, THBS1, and KRT17 are not only highly expressed in gastric cancer, but are also independent prognostic risk factors for gastric cancer." (PMID 34157940, 2021).
gastric cancer (continued). "EMT can also be initiated in gastric cancer by the β2-AR–metalloproteinase (MMP)-7 pathway through the activation of AP-1 and signal transducer and transcriptional activator 3 (STAT3)." (PMID 33670813, 2021). "Can inhibit the tumor growth in gastric cancer model and suppress the angiogenesis of the tumor by decreasing the expression of VEGF and MMP-7 in a mouse model with human gastric cancer." (PMID 34281199, 2021). "Pearson’s correlation coefficient displayed that gastric cancer outcome was significantly correlated with the expression of MMP7, CDH3, and LEF1 (p<0.05)." (PMID 34485109, 2021). "Gastric cancer remained related to MMP7, CDH3, and LEF1 (p<0.05) in the univariate linear regression model." (PMID 34485109, 2021). "Increased expression of SOX12 was related to gastric cancer cell migration, invasion, and metastasis via transcriptionally targeting matrix metallopeptidase 7 (MMP7) and insulin-like growth factor 1 (IGF1)." (PMID 34745940, 2021). "Catecholamine activity has been shown to upregulate MMP-7 levels through the β2-receptor adrenergic signaling pathway in gastric cancer cells." (PMID 34885041, 2021). "Matrix metalloproteinase-7 (MMP-7) is an enzyme responsible for the degradation of adherence between cells in the extracellular matrix, and overexpression of MMP-7 induces a more aggressive course of gastric cancer." (PMID 32340207, 2020). "MMP-7-positive tumor cells are predominantly found in the invasive front of gastric cancer, while their number is much higher in aggressive and late-stage tumors." (PMID 31344926, 2019). "For example, laminin γ2 expression combined with MMP-7 and EGFR expression in the invasive front is associated with gastric cancer aggressiveness." (PMID 31344926, 2019). "A meta-analysis also showed a significant poor prognostic effect of MMP-7 in gastric cancer survival." (PMID 31038586, 2019). "The results suggested the substantial role of MMP-7 in the creation of peritoneal dissemination in gastric cancer." (PMID 29867026, 2018). "Matrix metalloproteinase-7 (MMP-7) is an enzyme that plays a role in matrix degrading and impacts on the occurring of invasion and metastasis in gastric cancer patients." (PMID 29867026, 2018). "The MMP-7 protein level and mRNA expression were studied in primary gastric cancers and peritoneal dissemination." (PMID 29867026, 2018). "MMP-3 levels increase with tumor progression and elevated serum levels provide, in combination with MMP-7, a marker for poor prognosis in gastric cancer." (PMID 28398251, 2017). "Though MMP-7 increases drastically in gastric cancer, it is of low prognostic value as marker, unless combined with MMP-3." (PMID 28398251, 2017). "Due to the functioning of MMP their operation in cancer, Wang and colleagues performed a meta-analysis that showed the expression levels of MMP-7 were increased in gastric cancer." (PMID 28512631, 2017). "One study reported that CYR61 expression is inversely correlated with gastric cancer progression through regulation of expression of MMP-7." (PMID 27105510, 2016). "PTEN and AMPK proteins were frequently inactivated and p-mTOR, pS6, p4EBP1, and MMP7 proteins were frequently downregulated in human gastric cancer." (PMID 25909163, 2015). "Accordingly, in a future study, we intend to focus on the FGF/MMP7 axis in the context of gastric cancer cell invasion." (PMID 25925261, 2015). "Key proteins in mTOR pathway and MMP7 expressions were unfavorable prognostic factors for gastric cancer, while PTEN expression was a favorable prognostic factor." (PMID 25909163, 2015).